ARAF (A-Raf proto-oncogene, serine/threonine kinase)
Diseases named in the same sentence as ARAF in open-access papers (continued):
Sharing a sentence is not in itself a finding about the gene and the disease.
fibrosarcoma (3 papers, 2014 to 2024). A malignant mesenchymal fibroblastic neoplasm affecting the soft tissue and bone. "Recently, it has been discovered that RGS can interfere with RAS-signaling by binding to the RAS binding domains (RBD) of RAS-effector proteins (such as the rat fibrosarcoma (RAF) isoforms (ARAF, BRAF, and CRAF) and phosphatidylinositol 3-kinase (PI3K))." (PMID 29423069, 2018).
liver cancer (3 papers, 2021 to 2026). An epithelial or non-epithelial malignant neoplasm that arises from the liver. "In conclusion, we clearly demonstrate that CALR accelerates the growth of liver cancer cells by enhancing ARAF expression and telomere function (Fig. 1Z3)." (PMID 41262532, 2026). "Taken together, these observations suggest that CALR alters gene expression and the telomerase activity dependent on ARAF in liver cancer." (PMID 41262532, 2026). "In this study, we demonstrate that CALR accelerates the growth of liver cancer cells by enhancing telomere activity dependent on ARAF (A-Raf proto-oncogene, serine/threonine kinase)." (PMID 41262532, 2026). "Importantly, single-cell RNA sequencing showed that CALR affected the heterogeneity of liver cancer and its microenvironment network, involving ARAF." (PMID 41262532, 2026). "Next, we analyzed whether ARAF knockdown influenced the carcinogenic functions of CARM1 in liver cancer." (PMID 39415943, 2025). "Moreover, RNA sequencing and protein sequencing indicate that CALR could affect gene expression (e.g., ARAF) by altering transcriptome and proteome in human liver cancer cells." (PMID 41262532, 2026).
non-small cell lung carcinoma (3 papers, 2015 to 2021). A group of at least three distinct histological types of lung cancer, including non-small cell squamous cell carcinoma, adenocarcinoma, and large cell carcinoma. "Treatment with the oral RAF inhibitor, sorafenib, has demonstrated prolonged response in a case of refractory non-small-cell lung cancer and rapid responses in patients with refractory histiocytic neoplasms bearing somatic ARAF mutations." (PMID 28178681, 2017).
viral infection (3 papers, 2020 to 2025). "Some cases have been linked to viral infections, including Epstein–Barr virus, cytomegalovirus, human herpesviruses, and human immunodeficiency virus, as well as somatic mutations in genes such as NRAS, KRAS, MAP2K1 and ARAF." (PMID 41321345, 2025).
cardiac hypertrophy (2 papers, 2022 to 2024). "In particular, RAF kinases (ARAF/BRAF/RAF1) have already been identified as key regulators during cardiac hypertrophy in mice." (PMID 38892401, 2024). "RAF kinases (ARAF/BRAF/RAF1) integrate signals into the extracellular signal-regulated kinase 1/2 cascade, a pathway implicated in cardiac hypertrophy, and activation of BRAF in cardiomyocytes promotes compensated hypertrophy." (PMID 36331065, 2022).
dilated cardiomyopathy (2 papers, 2022 to 2023). Cardiomyopathy which is characterized by dilation and contractile dysfunction of the left and right ventricles. "Up-regulation of BRAF in separate cohorts of heart failure patients, with selective up-regulation of BRAF and down-regulation of RAF1 and ARAF isoforms in patients with dilated cardiomyopathy, suggests that the changes are a key feature of a failing heart." (PMID 35147166, 2022). "ARAF, BRAF and RAF1 transcripts were readily detected in human hearts, but only BRAF transcript expression was significantly increased in dilated cardiomyopathy samples; ARAF and RAF1 transcripts showed decreased expression." (PMID 35147166, 2022).
gallbladder cancer (2 papers, 2020 to 2024). "Taken together, ARAF silencing suppresses the malignant phenotypes of gallbladder cancer cells, and the mechanism may be associated with regulating Erk/cyclin D1 axis." (PMID 32923479, 2020). "In conclusion, our results demonstrate that ARAF expression is highly expressed in human gallbladder cancer, and ARAF silencing has an inhibitory effect on various phenotypes of GBC." (PMID 32923479, 2020). "Here, we found that ARAF expression was upregulated in gallbladder cancer tissues." (PMID 32923479, 2020). "After the expression level of ARAF gene was downregulated by RNA interference technology, the tumor phenotype of gallbladder cancer cells was considerably affected both in vivo and in vitro, which showed that the cell proliferation, metastasis, and other abilities were weakened." (PMID 32923479, 2020).
heart failure (2 papers, 2022 to 2023). Inability of the heart to pump blood at an adequate rate to meet tissue metabolic requirements. "BRAF and RAF1 (but not ARAF) mRNA and protein were significantly up-regulated in samples from a cohort of 12 patients with heart failure of mixed non-ischaemic aetiology compared with normal controls." (PMID 35147166, 2022).
astrocytomas (1 paper, 2023). "Thus, for tumors that are driven by BRAF dimers, such as low-grade astrocytomas with KIAA2549:BRAF, sparing of ARAF may provide an improved therapeutic window relative to pan-RAF inhibition." (PMID 36963492, 2023).
HCMV infection (1 paper, 2025). "To examine the contributions that ARAF or BRAF make toward HCMV infection, we targeted their expression via shRNA." (PMID 39902964, 2025).
lymphatic disease (1 paper, 2023). "It is recently reported that a recurrent gain-of-function ARAF mutation was found in a 12-year-old boy with advanced anomalous lymphatic disease unresponsive to conventional therapy." (PMID 36595106, 2023).
lymphatic malformation (1 paper, 2024). Primary lymphedema is caused by anatomic or functional defects in the lymphatic system, resulting in chronic swelling of body parts and lymphatic-system malformation. "The observation of ARAF variants in lymphatic malformations has not been replicated since." (PMID 38778413, 2024).
parathyroid adenomas (1 paper, 2023). "Previous studies described the important role of the MAPK/ERK pathway in parathyroid cell function, and its dysregulation in parathyroid adenomas, where HRAS, ARAF, and MEK1 genes are up-regulated and ERK is hyperactivated." (PMID 37065733, 2023).
RASopathies (1 paper, 2022). "Lymphatic anomalies were solidified as an important phenotypic feature when ARAF pathogenic variants, along with other RASopathy-associated genes, were recently identified in CCLA, a newly identified RASopathy." (PMID 35103797, 2022). "RAS then signals to numerous downstream effector pathways via serine/threonine kinase RAF (ARAF, BRAF and CRAF/RAF1), which, when dysregulated in the germline, causes RASopathies." (PMID 35103797, 2022).
small cell lung carcinoma (1 paper, 2024). Small cell lung cancer (SCLC) is a highly aggressive malignant neoplasm, accounting for 10-15% of lung cancer cases, characterized byrapid growth, and early metastasis. "RNA sequence analysis was performed in patients with ARAF amplification as well as presenting histologic transformations to small-cell lung carcinoma (SCLC)." (PMID 39456595, 2024). "Furthermore, we identified ARAF amplification in small-cell lung cancer (SCLC)-transformed tumors and characterized their phenotype." (PMID 39456595, 2024).
vascular malformation (1 paper, 2024). A non-neoplastic disorder that is the result of defects of vascular morphogenesis. "The remaining four genes (ARAF, CBL, GNB2 and PIK3CD) have been associated with vascular malformations with “limited evidence”." (PMID 38778413, 2024).
cancer (62 papers, 2005 to 2026). A tumor composed of atypical neoplastic, often pleomorphic cells that invade other tissues. "Mapping all of the ARAF mutations from the pan-cancer cohort highlights that the most prominent clustering occurs at position S214 (67 cases), followed by the adjacent position P216 (34 cases)." (PMID 40647542, 2025). "Activated KRAS binds and activates RAF family kinases (RAF1, BRAF, and ARAF), subsequently leading to uncontrolled proliferation and other processes causing cancer development and spread." (PMID 35141142, 2021). "By virtue of its apparent low activity and rare mutations in cancer genomes, the molecular mechanism regulating ARAF and its role in oncogenesis are ill-defined." (PMID 29930381, 2018). "Using published data of somatic mutations, iCAGES was able to replicate this finding by nominating ARAF as the first candidate cancer driver gene out of 129 genes with somatic mutations." (PMID 28007024, 2016). "It remains to be determined whether this mutation or other ARAF p.S214 mutations exhibit similar sorafenib sensitivity across different cancer types." (PMID 40647542, 2025). "Also, the ARAF gene mutation is a rare event in human tumorigenesis but is somatically mutated in human cancers." (PMID 39196408, 2024). "Since certain cancer genes (e.g. BRAF) share pathways with other more rarely mutated targets of driver alteration (e.g. ARAF, RAF1), it may be useful to consider mutational status in a set of genes as a predictive biomarker." (PMID 35803911, 2022). "In addition, ARAF comprises known functions involving cancer development such as activation of MAPK/ERK (associated with cell growth) and binding to pyruvate kinase isozymes M1/M2 (PKM2), critical for the Warburg effect." (PMID 29761043, 2018). "The identification of the ARAF p.S214C mutation as a potential biomarker for sorafenib responsiveness through the analysis of an exceptional responder case underscores the importance of comprehensive genetic profiling to guide and accelerate personalized cancer treatment strategies." (PMID 40647542, 2025). "The constitutive negative charge within the BRAF NtA region leaves the protein ‘primed’ for dimerisation, and able to be activated by single site phosphorylation or single point mutations; this may explain why BRAF mutations are far more common in cancer than ARAF or CRAF mutations." (PMID 33367512, 2021). "ARAF expression was elevated in cancer cells, and its inhibition significantly reduced cell proliferation and metastasis, promoted cell apoptosis, and suppressed p38MAPK pathway activation." (PMID 42205195, 2026). "The ExCy and Fujifilm’s mRNA transcripts in the Disease pathway were revealed by TCGA’s Cancer Gene Consensus analysis to be more likely mutated: MUC4, CDK4, and CD79A, ARAF, respectively." (PMID 40598203, 2025). "The first report demonstrated that ARAF overexpression reduces sensitivity to LXH254 in K/NRAS-mutant cancers." (PMID 41023593, 2025). "Rare but recurrent activating mutations in the other two RAF isoforms, ARAF and CRAF, have also been identified in diverse cancers." (PMID 41072765, 2025). "Despite these limitations, it is warranted to pursue the role of ARAF amplification in the pathogenesis of SCLC transformation in EGFR-TKI-treated cancers." (PMID 39456595, 2024). "Among ARAF-amplified cancers, we identified two cases with histologic transformation from adenocarcinoma to SCLC." (PMID 39456595, 2024). "The remaining two paralogs, ARAF and RAF1 (also known as CRAF) are less potent activators of MEK, and are rarely mutated in human cancers." (PMID 37079639, 2023). "ARAF alteration is a common indicator in cancer and contributes to tumor initiation, progression and metastasis." (PMID 38074096, 2023). "Additional amplifications were found in other cancer-related genes including ARAF, SF3B1 in CTCs and KIT in cfDNA." (PMID 35269713, 2022).
cancer (continued). "In ARAF-transformed NIH3T3 cells, PKM2 is changed from dimeric to a highly active tetrameric conformation, linking ARAF to cancer metabolism." (PMID 31941155, 2020). "In cancer genomes, BRAF is a major target of oncogenic mutations and a single-point mutation, and V600E represents >90% of events, while mutations in CRAF, ARAF, and KSRs are much less and have been detected in decreasing order of frequency." (PMID 31941155, 2020). "These instances are listed in the Dataset EV2 and they included, among others, RBL2, KLF5, and ARAF as homologs of cancer drivers RB1, PBX1, and BRAF, respectively." (PMID 29572294, 2018). "Oncogenic mutations in ARAF and CRAF also occur in cancer, though far less frequently than in BRAF." (PMID 41072765, 2025). "ARAF and CRAF mutations are far rarer in cancer and seem to behave like class 3 BRAF variants." (PMID 33367512, 2021). "ARAF encodes a scaffold that stabilizes BRAF: CRAF heterodimers and regulates RAF signaling; and specific inhibitors have been successful in phase I/II clinical trials in cancer patients." (PMID 25007077, 2014). "The RAF serine/threonine kinases (ARAF, BRAF and CRAF) are arguably the most important effectors of mutant RAS-dependent cancer growth, as they have a key driver role in RAS-mediated oncogenesis." (PMID 29184501, 2017). "In particular, four genes within pathways in cancer were differentially expressed in the same direction under all the three conditions, including HSP90B1, ARAF, and RUNX1, being downregulated, and CDK4, being upregulated under these three manipulations." (PMID 25007077, 2014). "Additionally, why cancer cells converge on ARAF rather than other RAF isoforms, and whether this reflects unique regulatory properties or protein interactions, warrants investigation." (PMID 41282105, 2025). "The absence of BRAF point mutations other than V595E in this study, and the lack of evidence for recurrent alterations in ARAF and RAF1, is globally consistent with observations in human cancers." (PMID 37079639, 2023). "Besides, the roles of seven genes (NR1D2, TANK, LRSAM1, PLXNA1, INHBE, HDGF, and ARAF) in SCLC have not been reported, however those genes have been reported to play a vital role in other type cancer." (PMID 34741430, 2021).
tumor (38 papers, 2004 to 2025). "Multivariate analysis confirmed that tumor localization and ARAF and MAPK10 mutations were independent predictive factors of reduced DFS (HR = 2.1; 95% CI: 1.1–4.0; p = 0.019; HR = 3.9; 95% CI: 1.2–13.1; p = 0.027; HR = 49; 95% CI: 9.8–244.1; p < 0.001)." (PMID 37835512, 2023). "Univariate analysis revealed that tumor localization in the right colon and ARAF and MAPK10 mutations were associated with reduced DFS." (PMID 37835512, 2023). "With L1000, ARAF p.V145L was determined to be neutral and ARAF p.D429A, ARAF p.S214C, ARAF p.S214F, were impactful variants and these variant function predictions were consistent with their effect on xenograft tumor formation and an erlotinib-rescue assay." (PMID 34214079, 2021). "Three tumours contained mutations in ERBB2/RAS/RAF/MEK pathway members or regulators: an ARAF mutation in combination with a NCK1 mutation, a PAK1 mutation in combination with a NF1 mutation, and an ERBB2 mutation in combination with a TSC1 mutation." (PMID 26506417, 2015). "RNA sequencing and reverse-phase protein array analyses demonstrated elevated expression of genes and proteins associated with tumor aggressiveness in the ARAF p.S214C mutants, and its sorafenib sensitivity was likely moderated through inhibition of the cell cycle and DNA replication." (PMID 40647542, 2025). "ARAF amplification potentially fosters conditions that promote tumor cell survival and neuroendocrine marker transcription under EGFR-TKIs, particularly in female patients with EGFR exon 19 deletion." (PMID 39456595, 2024). "ARAF amplification potentially fosters conditions that promote tumor cell survival and neuroendocrine marker transcription under EGFR-TKIs." (PMID 39456595, 2024). "The tumor mutation load showed BCL6 corepressor like 1 (BCORL1) and a-raf proto-oncogene (ARAF) have the highest copy number amplification, whereas lysine demethylase 6A (KDM6A) and RNA binding motif protein 10 (RBM10) showed the highest copy number deletion." (PMID 33629637, 2021). "Taken together, our results demonstrate that only BRAF is necessary during the early stages of NRAS-induced melanomagenesis, thereby revealing a specific function for BRAF in tumour initiation that cannot be compensated by ARAF and CRAF." (PMID 28497782, 2017). "Interestingly, two patients bearing metastatic lung adenocarcinoma displayed elevated allele frequencies of 0.62 and 0.95, respectively, suggesting the potential role of ARAF p.S214C in driving tumor aggressiveness and metastatic activity." (PMID 40647542, 2025). "Finally, two further downregulated genes were ICAM1, coding for CD54 protein driving tumor growth and ARAF, whose overexpression in HCC initiation and progression has been previously demonstrated." (PMID 38834875, 2024). "In addition, we found that the interaction network involving JHDM1D/KDM7A was associated with RAF1, ARAF, JAK2, and CAMK2 activation, reinforcing the involvement of JHDM1D/KDM7A in tumor aggressiveness and progression." (PMID 39136575, 2024). "The results suggested that the dysregulated AS events of ARAF regulated by SFs may become a novel part of the mechanisms of tumor relapse in HCC, which needs further experimental investigation." (PMID 36147313, 2022). "As RAF mutations, in analogy with RAS mutations, may show tumor type specificity, we sequenced exons 11 and 15 in BRAF and the equivalent exons in ARAF (exons 10 and 13) and RAF1 (exons 11 and 14)." (PMID 21533174, 2011). "Moreover, knocking down ARAF suppressed tumor growth in vivo." (PMID 32923479, 2020). "Tumor xenografts from H2023 cells expressing EGFP, ARAF-WT, and ARAF p.S214C in immunodeficient Nu/J mice were also generated, and their in vivo tumorigenicity and sorafenib response were compared." (PMID 40647542, 2025). "Along with previously reported genes such as WNT, we identify CAF-derived targets such as ARAF and COL3A1 upon which the tumor compartment depends for spheroid development." (PMID 29245949, 2017).
tumor (continued). "The sample was negative for ARAF amplification; however, the biopsied tumor after disease progression with etoposide and cisplatin followed by erlotinib identified ARAF amplification." (PMID 39456595, 2024). "Besides ARAF, CRAF has also been shown to have tumor suppressive properties in hepatocellular carcinoma." (PMID 35938171, 2022). "Analyzing the whole-blood expression signature of four growth factor-related genes (ARAF, BRAF, KRAS, and RAF-1) and four genes involved in metabolism (ATP6V1H, OAZ2, PANK2, and PLD3), combined with tumor grade, they were able to predict the efficacy of PRRT with an accuracy of 95%." (PMID 33809226, 2021). "To analyze the effects of daratumumab and of nanobody-based hcAbs on the GDPR cyclase activity of living CD38-expressing tumor cells, we incubated CD38-transfected HEK cells or LP-1 cells with CD38-specific hcAbs, daratumumab, or araF-NAD, before addition of NGD+." (PMID 33396591, 2020). "Likewise, mRNA levels of three oncogenes, namely ETS1, MDM2, and ARAF, were decreased by C treatment; on the contrary, the growth arrest and DNA-damage-inducible G (GADD45G), a stress-responsive gene involved in tumor suppression, was upregulated in C + AFB1 exposed cells." (PMID 33137966, 2020). "Notably, ARAF has a significantly lower kinase activity than BRAF and CRAF, but its overexpression prolonged the duration of MAPK activation, potentially creating conditions conducive to tumor cell survival and the transcription of neuroendocrine markers in the presence of EGFR-TKIs." (PMID 39456595, 2024).
hematological malignancies (1 paper, 2022). "Although three RAF kinases (ARAF, BRAF, and CRAF) play a physiological role in mammalian cells, BRAF is the most frequently altered kinase detected in a wide range of solid tumors and a subset of hematological malignancies." (PMID 35955671, 2022).
neurologic disease (1 paper, 2022). "Recent studies have identified NRAS, KRAS, MAP2K1, and ARAF mutations in RDD patients without documented neurologic disease." (PMID 35236371, 2022).